FOXO3 (forkhead box O3)
Diseases named in the same sentence as FOXO3 in open-access papers (continued):
Sharing a sentence is not in itself a finding about the gene and the disease.
tumor (continued). "Apart from the interaction with miR-135a, lncRNA UCA1 also inhibited miR-96, a tumor suppressor mRNA, resulting in the upregulation of forkhead box O-3 (FOXO3) to promote tumor progression." (PMID 33936199, 2021). "SOS1 has been shown to play a role in tumor growth in lung ADC35, while FOXO3 acts as a tumor suppressor by regulating apoptosis." (PMID 34117251, 2021). "In parallel to the GBM tumor analysis, we performed an in silico analysis of the FOXO3 TCGA network to identify the transcriptional co-regulators that coordinate with FOXO3 to instruct a stemness program." (PMID 36303712, 2021). "The number of tumor samples across studies ranged from 91 to 365, and 537 of the totals (50.71%) exhibited FOXO3 overexpression." (PMID 34771514, 2021). "The reduction of DKK1 activated the SGK3/FOXO3 pathway to accelerate cell migration and tumor metastasis." (PMID 33613114, 2021). "Previous evidence has provided verification of FOXO3 as a target gene of miR-29a-3p, and as a tumor-inhibitive transcriptional factor FOXO3 has been demonstrated to suppress the development of OC through its interactions with AKT." (PMID 34589270, 2021). "In this study, we used a constitutive active FOXO3 model to examine the tumor suppressor function of FOXO3." (PMID 33795838, 2021). "Overall, the miR-1247-5p/FOXO3 axis contributes to the tumor-promoting activities of LINC01124 in HCC cells." (PMID 37304672, 2021). "It is known that FOXO3 displays a dual role in cancer, promoting malignant phenotypes or inhibiting cancer progression depending on the tumor type or specific tumor-related circumstances." (PMID 34771514, 2021). "FOXO3 is a member of the FOXO transcription factors thought to play a tumor-suppressor role in gastrointestinal cancer, while tumor-promoting function of FOXO3 has also been reported." (PMID 33795838, 2021). "Autophagic Forkhead box O3a (FOXO3a) degradation also contributes to tumor tolerance to chemotherapeutic stresses by suppressing FOXO3a-mediated pro-apoptotic signals." (PMID 33809137, 2021). "Based on five studies involving 1059 cases, we found that high FOXO3 expression correlates with tumor development, poor survival and invasion in HCC." (PMID 34771514, 2021). "In the non-tumor tissues of the stomach, weak FOXO3 staining was detected in the cytoplasm of epithelial cells." (PMID 33795838, 2021). "FOXO3, a protein that belongs to the O subclass of the forkhead family of transcription factors, is a well-known tumor suppressor." (PMID 34381358, 2021). "The simultaneous activation of β-catenin and FOXO3 can prevent the death and promote the metastasis of tumor cells." (PMID 34123834, 2021). "Enrichment for categories associated with nucleotide and mitochondrial metabolism was observed in tumor samples with low FOXO3 expression." (PMID 36303712, 2021). "Consistently, simultaneous disruption of Foxo1, Foxo3, and Foxo4 in mice resulted in the development of thymic lymphoma and hemangiomas, supporting a possible tumor-suppressor role of FOXOs." (PMID 33795838, 2021). "A new SV cluster (cluster 3) identified in the primary tumour was generated with inverted repeats showing FOXO3 amplification." (PMID 33927198, 2021). "circFoxo3 binds to miR-22, miR-136, miR-138, miR-149, miR-433, miR-762, miR-3614–5p, miR-3622b–5p and promotes translation of Foxo3 mRNA, which is a tumor suppressor gene." (PMID 33763348, 2021). "Together, these findings indicate that hypoxia can promote the upregulation of miR-155 in EVs and that this miRNA can act in RCC cells to suppress FOXO3 expression, thereby enhancing cellular tumor progression." (PMID 33742606, 2021).
tumor (continued). "The circular form of Foxo3, circFoxo3, has demonstrated tumor suppressor as well as oncogenic potential, depending on the considered cancer context." (PMID 34202482, 2021). "FOXO3 is known as a tumor-inhibitive transcriptional factor and interacts with serine/threonine protein kinase (AKT) in OC." (PMID 34589270, 2021). "We, therefore, scored tumors based on the extent to which FOXO3 was located in the nucleus as either strongly nuclear in tumor cells (high activity) or mostly cytoplasmic in tumor cells, often weakly expressed (low activity)." (PMID 36303712, 2021). "The beneficial effect of FOXO3 inhibition by CBX was also evident in 3D-tumor-spheroids derived from high-stage NB8 cells." (PMID 31591479, 2020). "The FoxO family, which consists of FoxO1, FoxO3, FoxO4, and FoxO6, is known as a tumor suppressor that limits cell proliferation and induces apoptosis." (PMID 32508033, 2020). "FOXO3 functions downstream of the phosphatidylinositol 3-kinase-protein kinase B (PI3K-PKB/AKT) signalling pathway as a tumour suppressor, preventing uncontrolled cellular proliferation." (PMID 32615282, 2020). "FOXO3 also plays a dual oncogenic and tumor-suppressive role in cancer, therefore, multiple competing mechanisms should be taken into consideration in future study." (PMID 33207824, 2020). "In NB nuclear FOXO3 predicts adverse clinical outcome, promotes tumor angiogenesis, and mediates chemoprotection in the high-stage NB cell lines NB1, NB4, and NB8." (PMID 31591479, 2020). "Some of these proteins were tumor suppressors, including Rb, FOXO3, and p27, and many proteins were kinases and involved in the regulation of cell proliferation, differentiation, and apoptosis, such as c-KIT, AKT, EGFR, MAPK1/3, PRKCA, SRC, ACVRL1, and JNK2." (PMID 32917965, 2020). "The rescue assays indicated that the tumor-promoting effect of si-FOXO3 was alleviated by miR-940 inhibitor." (PMID 32840296, 2020). "FOXO3, a member of the forkhead type transcription factor family, has been reported to be an important tumor suppressor gene in various human cancers." (PMID 32840296, 2020). "Our own studies demonstrate that nuclear FOXO3 promotes tumor angiogenesis in vivo and chemoresistance in vitro in aggressive NB." (PMID 31591479, 2020). "Especially eradicating the FOXO3 activity in tumor stem cells would provide markedly improved therapeutic benefits to patients." (PMID 31591479, 2020). "FOXO3-silencing by 120 μM CBX in etoposide treated 3D-tumor-spheroids significantly impaired spheroid viability as measured by live-cell calcein-AM staining and by quantification of the cell viability by ATP content." (PMID 31591479, 2020). "FoxO3 has been proposed to regulate autophagy in glucocorticoid-treated and C-26 tumor bearing mice." (PMID 32425814, 2020). "FOXO3a (human protein Forkhead box O3) is a transcription factor from a family of transcription factors with tumor suppressor activity." (PMID 33198257, 2020). "Our previous studies demonstrated that shRNA against Ido1, Foxo3, Thbs1, and Clec4a2 can enhance the antitumor effect of Her2/neu DNA vaccine in the murine tumor model." (PMID 32933162, 2020). "Our results showed that miRNA‐96‐5p is an miRNA that functions as an oncogene, and FOXO3 is a tumor suppressor gene." (PMID 32100957, 2020). "These multiple levels of control of FOXM1 by FOXO3 emphasise the significance of FOXO3 as a tumour suppressor." (PMID 32372224, 2020). "The pro-survival phenotype of FOXO3 is also visible in 3D-tumor-spheroids, as FOXO3-activation significantly increases spheroid size and viability." (PMID 31591479, 2020). "Collectively, our work reveals a critical function for METTL3‐mediated m6A modification in the hypoxic tumor microenvironment and identifies FOXO3 as an important target of m6A modification in the resistance of HCC to sorafenib therapy." (PMID 32368828, 2020).
tumor (continued). "It has also been reported that the FOXO3 is a tumour suppressor gene commonly deleted during early-stage lung adenocarcinoma carcinogenesis." (PMID 32372224, 2020). "Further evidence comes from studies in genetically engineered mouse models (GEMMs), reporting that a complete loss of all six alleles of FOXO1, FOXO3, and FOXO4 dramatically induces the tumor phenotype." (PMID 32629884, 2020). "They increase PTEN (a negative regulator of Akt activation) in tumor cells, which results in higher accumulation of FoxO3 in tumor cells." (PMID 32793565, 2020). "It is reported that circ-Foxo3 is highly expressed in non-tumor cells and related to the cell cycle." (PMID 32774156, 2020). "FOXO3 expression seems to be necessary for the generation of uniform shaped 3D-tumor-spheroids as in this setting FOXO3-knockdown resulted per se in reduced spheroid size." (PMID 31591479, 2020). "Mechanistically, circRNA-FOXO3 increases the expression of FOXO3 by sequestering miR-155, and thus, functions as a tumor-suppressor gene." (PMID 32071550, 2020). "Like other tumour suppressors, FOXO3 is frequently downregulated or inactivated in different cancers and particularly, in drug-resistant cells, usually by deregulated hyperactive PI3K-AKT signalling." (PMID 32615282, 2020). "Multivariate analysis using a Cox proportional hazards model assessed the predictive value for MFS of the parameters found to be significant in univariate analysis, i.e. lymph node status and macroscopic tumor size, and FOXO3 protein expression (p = 5.5.10−3)." (PMID 32332845, 2020). "In line with the results of various studies, we provide experimental arguments suggesting a tumor suppressor activity of FOXO3 protein in breast cancer." (PMID 32332845, 2020). "FOXO3 is an evolutionarily conserved transcription factor involved in a wide spectrum of biological processes, including aging, apoptosis, and tumor." (PMID 33298101, 2020). "In humans, FOXO3 harbours tumour suppressor activity as it represses processes such as VEGFA-driven tumour angiogenesis." (PMID 30842454, 2019). "Previous studies revealed that up-regulated expression of circ-Foxo3 triggered stress-induced apoptosis and inhibited tumor growth." (PMID 31533653, 2019). "CircRNA forkhead box O3 (FOXO3) acts as a tumor suppressor via sponging miR-155 in NSCLC, and thus expression restoration of circRNA FOXO3 can be a new therapeutic option for NSCLC." (PMID 31885751, 2019). "In the current study, we identify a novel role of FOXO3 in controlling oxidative stress, which acts as a tumor promoter in hepatotoxin-induced tumor development." (PMID 31488102, 2019). "Deregulation of circ-Foxo3 and the Foxo3 pseudogene have been detected in tumor growth, and their upregulation has been found to suppress cancer by activating Foxo3 protein." (PMID 30774645, 2019). "Recently, Foxo3 gene was widely believed to be a tumor suppressor gene in many cancers, like breast and ovarian cancer." (PMID 31533653, 2019). "The tumor suppressor, circ-Foxo3, significantly downregulated in BC patients and cell lines, likely contributes to BC progression and its levels significantly increase when cancer cells undergo apoptosis." (PMID 31555649, 2019). "FOXO3-silencing by RPG further repressed the FOXO3-triggered 3D migration in tumor spheroids derived from high-stage SK-N-SH/FOXO3 cells." (PMID 31861249, 2019). "For instance, in breast and leukemia cancer cells, anti-cancer drugs inhibit tumor development via upregulation of FOXO3 and B cell lymphoma 2 like 11 (Bim) expression." (PMID 31540495, 2019). "FOXO3 is a tumor suppressor often deregulated in cancers, including glioblastoma, leukemia and breast and prostate cancer, due to its role in restricting cell proliferation and promoting cell death." (PMID 31357743, 2019). "In other tumor entities, FOXO3 stimulates metastasis formation, one of the biggest challenges in the treatment of aggressive NB." (PMID 31861249, 2019).
tumor (continued). "Forkhead box O3 (FOXO3) is a known tumor suppressor that represses cell-cycle progression and thus effectively represses abnormal cell division." (PMID 31272438, 2019). "Like other tumour suppressors, FOXO3 is frequently downregulated or inactivated in cancer and particularly, in drug-resistant cells, often as a result of hyperactive PI3K-AKT signalling." (PMID 31312024, 2019). "In line with this, FOXO3-knockdown attenuates tumor growth and metastasis formation in pancreatic ductal carcinoma and in glioblastoma xenografts." (PMID 31861249, 2019). "It is well documented that compounds that reactivated FOXO3 based on its tumor suppressor property are considered as very attractive anti-cancer therapy." (PMID 30655588, 2019). "Both, S9 and S9OX prevented FOXO3-induced cell death in 3D tumor spheroids at a concentration of 5 μM and after single administration." (PMID 31789593, 2019). "Our findings support the notion that a unique oncogenic JAK2 mediates the degradation of FOXO3 protein and contributes to an understanding of the control of FOXO3 protein in the tumor." (PMID 31540495, 2019). "Forkhead Box O3 (FOXO3) is a tumor suppressor whose activity is fine-tuned by post-translational modifications (PTMs)." (PMID 31357743, 2019). "FOXO3 deregulation plays essential roles in the development of cancer and thus FOXO3 has been classified as a tumor suppressor." (PMID 30953521, 2019). "Conversely, the expression levels of FOXO3 and its downstream transcriptional target p27Kip1 were low in the resistant cells but were comparatively much higher in MCF-7 cells, consistent with the role of FOXO3 as a tumour suppressor." (PMID 31312024, 2019). "In concordance, our own studies indicate that active FOXO3 promotes tumor angiogenesis in vivo and chemoprotection in vitro in high-stage NB." (PMID 31861249, 2019). "The expression of circRNA-Foxo3 has significantly increased during cancer cell apoptosis, which is experimentally explored the possibility of inhibiting tumor growth with the delivery of circ-Foxo3 plasmid." (PMID 31301674, 2019). "It is possible that other target genes of FOXO3 also contribute to the anti-tumor effects of FOXO3 in EOC." (PMID 31013711, 2019). "In pancreatic cancer treatment with EGCG suppressed tumour growth, accompanied by FOXO3 downregulation." (PMID 30563268, 2018). "The same study group additionally showed that circ-Foxo3 has a tumor suppressor function, independently of controlling the expression level of its host gene." (PMID 29911069, 2018). "Previous studies have showed that miR-629-5p involves in tumor progression via down-regulating FOXO3, Testis-specific Y-like protein 5, or TRIM33 in different types of cancer." (PMID 30042169, 2018). "In agreement, ROS-mediated activation of p38 MAPK and FOXO3 has been shown to have a pivotal role in the induction of differentiation and the repression of tumour-initiating capacity of human glioblastoma-derived glioma-initiating cells (GICs)." (PMID 29180117, 2018). "In a third paper, the authors confirmed that circ-Foxo3 is downregulated in breast tumor samples compared to benign mammary lesions." (PMID 29911069, 2018). "Ectopic expression of the Foxo3P, Foxo3 circular RNA and Foxo3 mRNA suppress tumor growth, and cancer cell proliferation and survival." (PMID 30071685, 2018). "By using in vitro and in vivo models of breast cancer it has been shown that the circ-Foxo3 has a tumor suppressor potential." (PMID 29911069, 2018). "Circ-Foxo3 was minimally expressed in patient tumor samples and in a panel of cancer cells and its expression was found to be significantly increased during the cancer cell apoptosis." (PMID 30598076, 2018).
tumor (continued). "Circ-Foxo3 is additionally able to block the interaction of MDM2 with Foxo3 and rise the expression level of Foxo3, increasing the apoptosis of tumor cells." (PMID 29911069, 2018). "Here, we showed that the transcription factor ZEB1, best known for promoting tumor progression, inhibits muscle atrophy and atrogene expression by antagonizing FOXO3-mediated induction of atrogenes." (PMID 30304480, 2018). "Foxo3 has been classified as a tumour suppressor gene due to the down-regulation of Foxo3 expression in cancer development due to increased Akt activity or loss of PTEN." (PMID 30157902, 2018). "FOXO3 inactivation has frequently been identified in human tumours, largely due to the overactivation of the PI3K-Akt pathway, and this FOXO protein is thought to coordinate the balance between cell proliferation and cell death." (PMID 29180117, 2018). "Collectively, our results suggest that SUMOylation positively regulates FOXK2 transcriptional activity and has a role in mediating the cytotoxic response to paclitaxel through the tumour suppressor FOXO3." (PMID 29540677, 2018). "Subcutaneous injection of MDA-MB-231 cells transfected with circ-Foxo3 into nude mice inhibits tumor growth and promotes apoptosis." (PMID 30064463, 2018). "For example, FOXO3 upregulates the cell-cycle inhibitor p27Kip1 and the retinoblastoma-related p130 (Rb2) tumour suppressor to induce G0/G1 arrest and the DNA damage-inducible protein 45 (GADD45) to induce G2 arrest." (PMID 29180117, 2018). "And systemic delivery of miR-10b-3p antagomir reduced tumor growth and inhibit FOXO3 protein expression in nude mice." (PMID 30514328, 2018). "We have shown increased expression of metastasis markers CXCR4, SDF-173,74 and decreased tumor suppressor molecules LDOC1 and FOXO3, induction of oncogenes and promotion of tumor growth." (PMID 30413788, 2018). "Our results also showed that MCF-7 cells overexpressing the K527/633 R mutant form of FOXK2 or the empty expression vector have lower protein and mRNA levels of its tumour suppressive transcriptional target FOXO3 compared to the wild-type FOXK2." (PMID 29540677, 2018). "Total FoxO3 protein levels were modestly increased in TA muscles from C26-tumor-bearing mice, in agreement with previous reports." (PMID 29167426, 2017). "We observed that FoxO3 recruitment at these promoters was remarkably increased in muscles from tumor-bearing mice, while FoxO3 occupancy at these sites was similar in muscles from control and (+)-JQ1-treated tumor-bearing mice." (PMID 29167426, 2017). "Surprisingly, FOXO3, known as the tumour suppressor plays the crucial role in the maintenance of CSC properties and FOXO3 knock down strongly suppressed CSC properties by downregulation of CD44, the essential protein for CSC properties." (PMID 29035170, 2017). "Foxo3 circular RNA (circ-Foxo3) increases Foxo3 translation and further suppresses tumor growth, cancer cell proliferation and survival by acting as a sponge of potential miRNAs." (PMID 28969093, 2017). "Studies have shown that FOXO3P, circ-Foxo3, and Foxo3 mRNA expressed elsewhere can inhibit the growth of a tumor." (PMID 28143578, 2017). "The pro-survival phenotype of FOXO3 was also visible in 3D-tumor-spheroids, where FOXO3-activation significantly increases spheroid-size and viability as measured by ATP-content." (PMID 28869600, 2017). "Both p-AMPK(Thr172) and p-FoxO3(Ser413) levels were comparable in muscles from (+)-JQ1-treated C26-tumor-bearing mice and control animals." (PMID 29167426, 2017). "Overall, 45.2% of all tumours had a functional mutation in at least one member of the Akt signalling pathway (PIK3CA, AKT1, PIK3R1, PTEN and FOXO3)." (PMID 27161491, 2016).